ALB (albumin)
Diseases named in the same sentence as ALB in open-access papers (continued):
Sharing a sentence is not in itself a finding about the gene and the disease.
tumor (continued). "Moreover, S100P-SPP1 + iCCApps harbors tumor cells at different status of differentiation, such as ALB + hepatocyte differentiation and ID3+ stemness." (PMID 35347134, 2022). "Albumin is an interesting target in terms of tumor targeting and drug delivery in chemotherapy." (PMID 35890274, 2022). "To explore the mechanism by which SOX8 affect sensitivity to Nab-p treatment in PDAC, we tested whether SOX8 would affect albumin uptake in tumor cell." (PMID 35173526, 2022). "Albumin-dye nanocomplexes reported by Zeng, Liu, and co-workers and the heptamethine cyanine near-IR dye-containing compound reported by Gong, Cai, and co-workers both require relatively long times for specific tumor imaging (10 h to days)." (PMID 35884281, 2022). "The purpose of the study was to evaluate whether the modification improves tumor retention in vivo and which albumin binder better matches FAPI molecules." (PMID 34593598, 2022). "Taken together, conjugating the PD-L1 aptamers to albumin may prolong circulating time and improve tumor-targeting via the ERP effect, resulting in augmented anticancer efficacy in vivo." (PMID 35268583, 2022). "Tumour onset was defined as when M-spike levels were equal to or higher than serum albumin levels." (PMID 36435864, 2022). "After adjusting for age, sex, tumor site, tumor size, tumor differentiation, ASA classification, TNM stage, hemoglobin, and albumin, the risk of postoperative death in the transfusion group was 2.747 times higher than that in the non-transfusion group (HR = 2.747, 95% CI, 1.048–7.205)." (PMID 35937600, 2022). "Therefore, the use of fatty acids as albumin binders is a promising strategy for development of peptide-based radiopharmaceuticals as long-term tumor-targeted radiotherapy agents for clinical application." (PMID 35890224, 2022). "In vivo, oxygen-saturated albumin NP selectively accumulated in tumor and increased oxygenation." (PMID 35624636, 2022). "The average age of the patients was 60 years old (28–86 years old), the average maximum diameter of the tumor was 2.24 ± 1.17 cm, the average hemoglobin was 131.93 ± 20.08 g/L, the average albumin was 42.45 ± 3.77 g/L, and the average prealbumin was 254.13 ± 65.56 mg/L." (PMID 36684356, 2022). "Albumin inhibits tumor progression by stabilizing DNA replication and enhancing immune responses." (PMID 36387142, 2022). "Interestingly, low expression in tumor cells has been shown to limit recycling of albumin, leading to enhanced growth by increasing tumor cell consumption of albumin." (PMID 35378997, 2022). "In vitro, albumin has been shown to suppress tumor proliferation." (PMID 36467502, 2022). "Additionally, in vivo studies have also shown that albumin–artemether nanoparticles can control tumor growth by increasing the production of cytokine IFN-γ and decreasing the production of IL4." (PMID 36359230, 2022). "There is a high probability that albumin with an increased diameter after binding to CR–Dox and additionally after possible dimerization will not penetrate through healthy vessels, but it will easily penetrate the vessels surrounding the tumor." (PMID 35563426, 2022). "Various pro-inflammatory cytokines can regulate the synthesis of albumin in the hepatocytes as part of the tumor inflammatory response and, at the same time, can promote tumor growth and metastasis, destroy the host’s immune response, and promote drug resistance." (PMID 36290873, 2022).
tumor (continued). "The resulting overall score, DyAM risk, was used as input to a multivariable Cox proportional hazards model with derived neutrophil-to lymphocyte ratio (dNLR), pack-years smoking history, age, albumin, tumor burden, presence of brain and liver metastases, tumor histology and scanner parameters." (PMID 36038778, 2022). "Due to the large tumor at the time of diagnosis and poor quality of life, the patient was intolerant to surgery, so she was given radiotherapy (RT) combined with concurrent chemotherapy (CT) with albumin bound paclitaxel." (PMID 36147925, 2022). "In addition, tumor length,number of tumors, BCLC stage, local invasion, ALB, ALT, AST, and ALP were also independent risk factors affecting OS; and GGT and tumor length were also independent risk factors affecting RFS." (PMID 35282826, 2022). "Also, albumin-bound nanoparticles can enrich the chemotherapeutic drugs in tumor tissue through the interaction with drug transport receptors, thereby increasing the antitumor activity." (PMID 36331291, 2022). "On the other hand, due to excessive consumption by tumour progression and impaired protein synthesis ability, serum ALB levels might be decreased." (PMID 35945520, 2022). "The AUC for PLR, WBC, hemoglobin, fibrinogen, albumin, globulin, tumor diameter, PNI, and NLR, were 0.639 (P < 0.001), 0.525 (P = 0.284), 0.594 (P < 0.001), 0.625 (P < 0.001), 0.587 (P < 0.001), 0.512 (P = 0.614), 0.749 (P < 0.001), 0.626 (P < 0.001) and 0.594 (P < 0.001), respectively." (PMID 35340978, 2022). "Furthermore, the multivariable analyses showed that White race, higher albumin level, younger age, and lower level of tumor marker CA 19-9 were significantly predictive of better survival." (PMID 36475189, 2022). "In addition, albumin can readily infiltrate tumor tissue and has been shown to enhance intra-tumoral accumulation." (PMID 35962391, 2022). "High concentrations of ALB significantly inhibits the growth of various tumor cells." (PMID 35719922, 2022). "The slow release of PS in the presence of albumin from the micelles makes it advantageous to exhibit the EPR effect because it is known to take hours to exhibit the EPR effect-based tumor accumulation; i.e., PS micelles need to remain stable during circulation until it accumulates in the tumor." (PMID 35330492, 2022). "Univariate analysis showed that the presence of SML during neoadjuvant therapy, tumor diameter, mitotic index, baseline albumin, and whether to continue imatinib therapy postoperatively were significantly associated with 3-year survival." (PMID 36028812, 2022). "Low CXI was significantly associated with a more advanced tumor–node–metastasis (TNM) stage, a higher level of serum C-reactive protein, serum interleukin-6, and NLR, but also a decreased level of serum prealbumin and albumin." (PMID 36139560, 2022). "No studies have associated SMAD14 or its tumor suppressor properties to either general liver health and function or specifically to serum albumin regulation." (PMID 36303554, 2022). "A second promising approach in tumor therapy is nanoparticles (NPs) stabilized by albumin." (PMID 36145639, 2022). "Therefore, despite the increased hydrodynamic size of scFv, it can be expected that in vivo distribution will be enhanced compared to unmodified scFvs or monoclonal antibody, due to increased blood circulation time and albumin’s own selectivity toward tumor." (PMID 36145517, 2022). "In the bloodstream, paclitaxel was delivered to tumor lesion in an albumin-bound form." (PMID 35954319, 2022). "The albumin levels and inflammation are closely related to tumor prognosis." (PMID 36684183, 2022).
tumor (continued). "Albumin is a commonly applied indicator to evaluate a patient's nutritional and immune status, and it can stabilize DNA replication and enhance the immune response, thereby inhibiting tumor progression." (PMID 35606690, 2022). "The anti-cancer cell proliferation and anti-tumor proliferation effects were studied in vitro and in vivo, proving that pre-coating the functional biomimetic albumin is an excellent and promising strategy for better drug delivery efficiency and therapeutic effects." (PMID 36134930, 2022). "Considering both tumor- and liver function-related factors, the hepatoma arterial-embolization prognostic (HAP) score (including tumor size, bilirubin, albumin, and α-fetoprotein (AFP)) has exhibited a promising prediction performance in uHCC patients following TACE." (PMID 36776366, 2022). "The patients with high IINS were more likely to have higher BCLC stage (P = 0.001), Child-Pugh grade (P < 0.001), NLR (P < 0.001), PLR (P = 0.002), SIRI (P = 0.030) and hsCRP levels (P < 0.001), more tumor numbers (P = 0.031), but lower ALB (P < 0.001) and LYM (P < 0.001) levels." (PMID 36016629, 2022). "Moreover, the uptake of extracellular proteins is markedly activated in rapidly growing tumor cells, albumin being the major nutritional source for the tumor and, in this way, the major site of serum albumin catabolism." (PMID 35888170, 2022). "MAPK/ERK pathway inhibition may block macropinocytosis and tumor uptake of albumin, therefore reducing the potential advantages of albumin binding for drug delivery." (PMID 35486732, 2022). "Nab-paclitaxel is a nanoparticle-sized anti-tumor drug formed from paclitaxel and albumin." (PMID 36406211, 2022). "This selective distribution at the tumor level suggests that a decrease in chemotherapeutic adverse effects could be also achieved with these albumin-based formulations." (PMID 35267507, 2022). "Moreover, albumin can bind to many endogenous ligands, such as physiologically significant fatty acids that can affect metabolism and tumor proliferation." (PMID 36359230, 2022). "Thus, albumin nanocarriers can deliver drugs into tumor sites with the specific targeting of folate receptors, glycoproteins, growth factors, integrins and organelles." (PMID 35203695, 2022). "In addition to the EPR effect, the gp60 receptor located in tumor blood vessel endothelium, which transports albumin through transcytosis into the tumor interstitium, contributes to MID:BSA accumulation in tumors." (PMID 35888170, 2022). "The new compound TetraVV binds the albumin in a dose-dependent manner and has pH-dependent stability in biological media, properties which ensure its internalization by the tumor cells and facilitate its release into the cell, where it exerts the biological activities." (PMID 35740239, 2022). "Our results showed that patients with CRP/ALB > 1.9 before tumor removal had shorter PFS and OS." (PMID 35873678, 2022). "We therefore hypothesize that serum albumin may be a key modulator of tumor response from cancer immunotherapies." (PMID 35393553, 2022). "Albumin is a good candidate as drug carrier because of its long half-life and continuous uptake in tumor tissue, which could enhance EPR effect." (PMID 34541384, 2022). "Accordingly, we speculated that reassembling of abPTX to acquire denatured albumin nanoparticles (NP-abPTX), which could be engulfed by local RT-activated neutrophils, might alleviate systemic side effects and promote tumor targeting drug delivery." (PMID 35244505, 2022). "Little in vivo preclinical and clinical research has been performed with radiolabeled MMPs, because no radiolabeled MMP currently has an optimal balance between target affinity, hydrophilicity, and intrinsic albumin affinity, for optimal tumor accumulation and tumor-to-background ratios." (PMID 35788730, 2022).
tumor (continued). "Univariate analysis revealed that serum albumin, tumor size > 30mm, hepatectomy of 1 segment or more, 2 segments or more, resection containing S8 area, open hepatectomy, intrahepatic diaphragm incision, operation time ≥ 360 min, and intraoperative blood loss ≥ 500mL were associated with sPOPE." (PMID 34095728, 2021). "The univariate Cox regression analysis identified that serum albumin (HR = 0.87; 95% CI = 0.78–0.97; P = 0.013), tumor diameter (HR = 1.29; 95% CI = 1.09–1.53; P = 0.004), and PNI (HR = 0.17; 95% CI = 0.07–0.39; P = 0.01) were significant prognostic factors associated with RFS." (PMID 32026332, 2021). "Likewise, the conjugation of boron-containing drugs with serum albumin would not only prolong the half-life of the drugs but also allow for the drug accumulation at the targeted tumor site." (PMID 34770947, 2021). "Serum albumin (HR = 0.88; 95% CI = 0.81–0.95; P = 0.001), tumor diameter (HR = 1.19; 95% CI = 1.08–1.32; P = 0.001), PNI (HR = 0.31; 95% CI = 0.17–0.57; P = 0.02), and SII (HR = 2.08; 95% CI = 1.15–3.76; P = 0.016) were significant prognostic factors associated with OS." (PMID 32026332, 2021). "For example, albumin-based nanoparticles expressing transferrin receptor binding peptide T12 and mannose were capable of not only polarizing M2 TAMs to become M1, but also remodeling the tumor microenvironment to allow for an enhanced anti-tumor response." (PMID 33790906, 2021). "Similar data were published by Park and collaborators who noticed effective accumulation of 64[Cu]-labeled-click chemistry-based albumin nanoplatform conjugates in normal lung, liver, kidney, intestine, and heart with an over four-fold higher uptake than the tumor at 1 h post-injection." (PMID 33920299, 2021). "Additionally, the hepatocytes formed 3D structures and maintained increased functionality in albumin synthesis and ammonia metabolism, which are limited in tumor-derived or immortalized cell lines." (PMID 34335954, 2021). "Owing to the specific binding affinity between albumin and overexpress receptors of cancer cells, the formed albumin nanoparticles could accumulate at tumor site via enhanced permeability and retention (EPR) effect and receptor-mediated endocytosis." (PMID 33407570, 2021). "Firstly, it was a retrospective study, and some data were not available in all patients, such as baseline albumin, weight loss during treatment, and changes in tumor markers, and leukocyte and lymphocyte counts." (PMID 34488754, 2021). "Taken together, any impairment in ALB-mediated function may lead to the emergence of an extremely aggressive tumor phenotype characterized by enhanced tumor cell proliferation, growth, widespread metastasis, and resistance to anticancer treatments." (PMID 33927759, 2021). "The enhanced permeability, permeation, and retention (EPR) effect of the meso-chloride on a rigid cyclohexenyl ring of ZW800-Cl enabled ZW800-Cl to form a covalent complex with albumin and then penetrated the tumor cells via the overexpressed albumin receptors in cancer cells." (PMID 35222006, 2021). "WHO PS ≥ 1, tumor stage IV, the presence of active brain metastases, ≥2 metastatic sites, baseline corticosteroid use, ALB < LLN, LDH ≥ ULN, CRP ≥ 2ULN, ALC < 750/mm3, NLR ≥ 5, and TMTV ≥ 80 mL were significantly associated with worse PFS and OS in univariate analysis (p ≤ 0.047)." (PMID 33418936, 2021). "Binding to both albumin and tumor cells was determined by ELISA-based assays." (PMID 33859761, 2021). "Predictors of TGR included elevated AFP, low albumin, and smaller tumor size." (PMID 34966854, 2021).
tumor (continued). "Multivariate regression analysis of these factors showed that current smoking, albumin, prealbumin, AFP, varicose veins of gastric fundus, BDTT, macrovascular invasion, MVI, tumor number, and maximal tumor diameter as independent risk factors of survival of patients with HCC." (PMID 34976789, 2021). "Gao and his colleagues designed and constructed a novel nanoparticle HSA/dc-825/GA through self-assembly of human serum albumin (HSA), dc-IR825, and gambogic acid (GA), which can cause the synergistic effect of mild PTT and chemotherapy to persistently and effectively ablate the tumor." (PMID 35222006, 2021). "In addition, we discuss various surface modification strategies to improve the internalization, efficacy, and specific tumor targeting of the albumin nanocarriers." (PMID 34298666, 2021). "Studies suggest that the acidic environment of the tumor may facilitate the release of the covalent adducts from albumin through acidic cleavage." (PMID 34141613, 2021). "The expression level of ALB was upregulated in BLCA tumor tissue compared with normal tissues." (PMID 34422642, 2021). "These albumin-based nanoparticles presented excellent properties in PC-3 xenograft models, where the nanoparticles accumulated in the tumoral area, and lead to a significant reduction in tumor volume (80%)." (PMID 34298666, 2021). "Albumin can be a multifunctional protein carrier system for tumor therapy." (PMID 34977115, 2021). "In univariate analyses, serum albumin was also a predictive factor; additionally, we consider that the immunosuppressive tumor microenvironment (indicated by a higher serum CRP) may play a critical role in nivolumab treatment." (PMID 33635904, 2021). "Similar reduction of tumor growth, enhanced uptake, and prevention of metastasis with docetaxel was achieved with other nano-formulations, such as nanoliposomes, albumin conjugates, Ecoflex® nanoparticles, and human serum albumin nanoparticles." (PMID 33925129, 2021). "In addition, we found a tendency that an elevated AMC was significantly associated with some clinicopathological characteristics including gender, T stage, vascular invasion, tumor length, and smoking, as well as higher platelet counts and lower albumin." (PMID 33591628, 2021). "Importantly, highly accumulated Al-ProD in the tumor tissues via albumin-mediated passive targeting selectively released doxorubicin in cathepsin B-overexpressed cancer cells, which provoked potent antitumor efficacy." (PMID 35056979, 2021). "Although the EPR effect and the interaction of albumin with gp60 receptor and SPARC can enhance the accumulation of drug-loaded albumin nanoparticles in tumors, they still have some drawbacks, such as insufficient tumor targeting and weak tumor tissue penetration." (PMID 34869202, 2021). "Elevated D-dimer levels were significantly associated with a high platelet level (p = 0.002), a low albumin level (p < 0.001), a high NLR level, a high CA19-9 level (p = 0.005), pancreatic head cancer (p = 0.012), poor tumor differentiation (p = 0.014), and less adjuvant chemotherapy (p < 0.002)." (PMID 34107980, 2021). "Other parameters for poor prognosis were female sex (HR = 1.6, 95% CI 1.1–2.4, p = 0.017), serum albumin < 35 g/L (HR = 1.5, 95% CI 1.1–2.2, p = 0.03), primary tumour location of the gallbladder (HR 2.3, 95% CI 1.4—3.5, p < 0.001) and high dNLR (HR 1.8, 95% CI 1.1–3.0, p = 0.031)." (PMID 34298723, 2021). "Besides, the ALT, ALB, TBIL, Child–Pugh grade, LMR and tumor diameter were also associated with the PRG (all p < 0.001)." (PMID 33676467, 2021). "This suggests that SPARC could also play a role in tumor uptake of albumin-bound HMCDs, but direct evidence for the uptake of HMCDs is lacking." (PMID 34141613, 2021). "The Al-ProD binds to in situ albumin, and albumin-bound Al-ProD indicates high tumor accumulation with prolonged half-life, and selctively releases doxorubicin in cathepsin B-overexpressed tumor cells, inducing a potent antitumor efficacy." (PMID 35056979, 2021).